BRCA1 (BRCA1 DNA repair associated)
Diseases named in the same sentence as BRCA1 in open-access papers (continued):
Sharing a sentence is not in itself a finding about the gene and the disease.
breast cancer (continued). "We estimated that mutations in BRCA1 and BRCA2 explain 32% of breast cancer FRR for relatives of patients with ER-negative and 9.4% of the breast cancer FRR for relatives of patients with ER-positive disease." (PMID 20146796, 2010). "BRCA1 carriers who are older at first breast cancer diagnosis are more likely to have ER+ tumors than younger BRCA1 carriers." (PMID 20149218, 2010). "However, approximately 20% of breast cancers that develop in BRCA1 carriers are ER-positive (ER+); these cancers are more likely to develop as BRCA1 carriers age, suggesting that they may be incidental and unrelated to BRCA1 deficiency." (PMID 21080930, 2010). "This is consistent with the 31% frequency of ER+ BRCA1 breast cancers recently reported in the retrospective series by Atchley and colleagues." (PMID 20149218, 2010). "Given the uniformity of many of the pathologic features of the BRCA1 ER- breast cancers in this study, we think it is unlikely that this substantially affected the major findings of our study." (PMID 20149218, 2010). "BRCA1- and BRCA2-mutated breast cancers are associated with increased amounts of chromosomal aberrations, presumably due their functions in genome repair." (PMID 20735817, 2010). "Collectively, it is obvious that BRCA1 and/or BRCA 2 mutations have been found to account for a greater proportion of breast cancer patients among the studied families." (PMID 20579331, 2010). "Sixty breast cancer patients, derived from 60 families, were selected for molecular genetic testing of BRCA1 and BRCA2 genes." (PMID 20579331, 2010). "For example, for breast cancer diagnosed at age 30, the BRCA1 carrier probability is estimated to be 0.19 when the tumour is TN and 0.02 when the tumour is ER-negative but not TN." (PMID 20482762, 2010). "The results of this study suggest that BRCA1 carriers who are older at the time of diagnosis of their first invasive breast cancer are more likely to have an ER+ breast cancer than are BRCA1 carriers who are younger at diagnosis." (PMID 20149218, 2010). "There have been several case control studies seeking BRCA1 and BRCA2 variants associated with an increased risk of breast cancer." (PMID 20807450, 2010). "On the other hand ID4 was identified as an upstream regulator of BRCA1 in breast and ovarian cancer, and more aggressive breast cancer types showed higher ID4 expression." (PMID 20070914, 2010). "This difference was also maintained in BRCA1 carriers with respect to BRCA1-negative and sporadic breast cancer patients." (PMID 20219108, 2010). "BRCA1 and BRCA2 mutation carriers are at increased risk for developing breast cancer and/or ovarian cancer." (PMID 21114847, 2010). "We therefore set out to compare frequency of LVI in a large set of BRCA1 related breast cancers with well matched sporadic controls." (PMID 20398395, 2010). "There are several possible explanations for our observation that the histopathology of ER+ BRCA1 breast cancers differs significantly from both ER- BRCA1 cancers as well as ER+ sporadic breast cancers." (PMID 20149218, 2010). "In a study of 51 sporadic breast cancer patients, those with high levels of BRCA1 attained better response to anthracycline-based chemotherapy, though overall survival was not examined." (PMID 20209131, 2010). "First, it may be that although some ER+ BRCA1 breast cancers develop from complete loss of BRCA1 function, others still have intact BRCA1 function resulting in tumors that as a group have phenotypic features that are intermediate between ER- BRCA1 and ER+ sporadic breast cancers." (PMID 20149218, 2010). "Germline mutations in either of the two predisposing genes, BRCA1 and BRCA2, account for a significant proportion of hereditary breast cancer." (PMID 20579331, 2010).
breast cancer (continued). "Breast cancers initiated in women who are heterozygous for BRCA1 or BRCA2 often have a reduction to homozygosity at the BRCA-locus eliminating its functions." (PMID 20111735, 2010). "It was initially reported that BRCA1 overexpression in human breast cancer cell lines resulted in increased resistance to DNA-damaging chemotherapy." (PMID 20209131, 2010). "Pushing margins have been reported to be significantly more often present and to cover a larger area of the tumor in BRCA1 and -2 related breast cancers." (PMID 20398395, 2010). "Our study was performed to identify germline mutations in some exons of BRCA1 and BRCA2 genes for the early detection of presymptomatic breast cancer in females." (PMID 20579331, 2010). "We have demonstrated that BRCA1 is methylated both in breast cancer cell lines and breast cancer tumor samples." (PMID 20614009, 2010). "Data on the distribution of ER status for BRCA1 or BRCA2 breast cancer tumours were obtained from a study conducted by the BCLC." (PMID 20482762, 2010). "Although inherited mutations in a small number of genes account for only about five to ten percent of women's cancers, by far the BRCA1 and BRCA2 gene mutations are the most common examples of this observation (50–70% of familial breast cancers)." (PMID 20111735, 2010). "One of these genes is BRCA1, whose decreased expression was often observed in breast cancer with epigenetic silencing and mono-allelic deletion of the BRCA1 gene." (PMID 20230646, 2010). "Hypermethylation of one or more genes (BRCA1, p16, and 14-3-3σ) was found in 95% of sporadic breast cancers." (PMID 24281040, 2010). "BRCA1-depleted breast cancer cells have previously been shown to be sensitive to CDK2 depletion or inhibition." (PMID 20010939, 2010). "Our study involves a very large number of Caucasian patients with breast cancer (N = 5923) who were first evaluated for their family history of breast cancer and subsequently for BRCA1 status." (PMID 20219108, 2010). "Meanwhile, loss or reduction of BRCA1 and BRCA2 expression has been exhibited in sporadic breast cancers." (PMID 20230646, 2010). "Preclinical breast cancer studies suggest a role for BRCA1 in predicting response to DNA-damaging agents and taxane-based chemotherapy." (PMID 20209131, 2010). "The median age of breast cancer onset ranges from 40-50 years in BRCA1 and BRCA2 carriers compared with 60-70 years in sporadic cases." (PMID 20961453, 2010). "For relatives of carriers, the female breast cancer SIRs were 13.13 (95% CI 6.57–26.26) and 12.52 (5.21–30.07) for BRCA1 and BRCA2, respectively." (PMID 20877337, 2010). "The series had been used previously to determine the frequency of mutations in the BRCA1, ATM, NBS1 and CHEK2 genes as well as to characterize more common polymorphisms studied by the Breast Cancer Association Consortium." (PMID 21108795, 2010). "Of note, only 4% of ER+ BRCA1 breast cancers possessed all three of these features and 67% lacked all three features (compared with 50% and 3%, respectively, of ER- BRCA1 breast cancers)." (PMID 20149218, 2010). "BRCA1 and BRCA2 mutations are found in a proportion of families with multiple early-onset breast cancers." (PMID 20807450, 2010). "This reduction of BRCA1 mRNA levels in sporadic breast cancer cases has been related to acquired methylation of the BRCA1 promoter and to abnormalities in the upstream pathways that regulate BRCA1 expression." (PMID 20209131, 2010). "In conclusion, chemotherapy has a greater protective effect in BRCA1 mutation carriers compared with patients who are BRCA-negative and those with sporadic breast cancer." (PMID 20219108, 2010).
breast cancer (continued). "Here we demonstrate for the first time that BRCA1 is methylated both in breast cancer cell lines and breast cancer tumor samples at arginine and lysine residues through immunoprecipitation and western blot analysis." (PMID 20614009, 2010). "In conclusion, the results of this study indicate that BRCA1 carriers who are older at the time of invasive breast cancer diagnosis are more likely to have ER+ breast cancers than younger BRCA1 carriers." (PMID 20149218, 2010). "Although only 29% of the breast cancers that developed in pre-menopausal BRCA1 carriers were ER+, 53% of the cancers in post-menopausal women were ER+." (PMID 20149218, 2010). "It should be noted that more of the BRCA1 ER- breast cancers identified were unavailable for pathologic review." (PMID 20149218, 2010). "Pathologic material was available for 49 of the 58 ER+ BRCA1 cancers and for 68 of the 114 ER- BRCA1 breast cancers." (PMID 20149218, 2010). "Third, BRCA1 related breast cancers are frequently (11-19%) of the medullary tumor type, in contrast to 1% of sporadic cancers." (PMID 20398395, 2010). "In some populations BRCA1 and BRCA2 mutations can account for ten percent of all breast cancers (Ashkenazi Jewish populations) and ovarian cancers but in many ethnic groups and in all populations taken together these mutations are much rarer." (PMID 20111735, 2010). "We divided breast cancer into distinct disease end points and used data on the proportion of ER-negative and ER-positive tumours in BRCA1 and BRCA2 carriers and the general population to derive age-specific incidences of ER-negative and ER-positive disease." (PMID 20482762, 2010). "Actually, BRCA1 expression levels measured by the immunocytochemical assay were significantly lower in three basal-like breast cancer cell lines." (PMID 20959018, 2010). "Sequencing data of exon 22 of BRCA1 gene which amplified from healthy woman (control) and patient with breast cancer, the alignment was carried out using Clustal W 1.9 program." (PMID 20579331, 2010). "Since other dietary polyphenols including resveratrol and indole-3-carbinol have been shown to induce expression of the BRCA1 protein in breast cancer cells, we examined the effect of curcumin on BRCA1 in TNBCs." (PMID 19809577, 2009). "Rare mutations in the coding sequence of BRCA1 and BRCA2 and a growing number of other genes involved in maintaining genomic stability have been shown to confer high to moderate risks of breast cancer." (PMID 19183483, 2009). "Thus, CTBE cells showed both p63 and CK5 over-expression together with a significant loss of BRCA1 expression and ER negativity, all consistent basal breast cancer phenotype, which may indicate a loss of differentiation capacity during the acquisition of basal malignant phenotype." (PMID 20049202, 2009). "Female carriers of BRCA1 and BRCA2 mutations have an estimated 50–90% life-time risk to develop breast cancer, classifying both genes as high-risk susceptibility genes." (PMID 19607694, 2009). "Mutations in the BRCA1 and BRCA2 tumour suppressor genes have been associated with the breast cancer risk among families with strong recurrence of the disease." (PMID 19232099, 2009). "Disease onset age of breast cancer did seem to vary according to MDM2 309SNP genotype in the BRCA1/2 groups." (PMID 19226467, 2009). "No interactors were found for TMEM57, possibly reflecting its role in the classifier as the pivot gene, while the other two genes showed interactions with many other proteins involved in breast cancer biology including the BRCA1 protein itself." (PMID 19695104, 2009).
breast cancer (continued). "Another mouse model for basal-like breast cancer was generated by conditional deletion of Brca1 exons 22–24 (which harbour the second BRCT domain) in the mammary gland by using β-lactoglobin (BLG)-cre." (PMID 19904273, 2009). "Target ssDNA related to the BRCA1 breast cancer gene were modified with multiple copies of AP through a streptavidin-biotin bond, and exposed to the probe ssDNA-modified beads for hybridisation." (PMID 22346717, 2009). "We investigated this topic by assessing XIST behaviour in different groups of breast carcinomas and in a panel of breast cancer cell lines both BRCA1 mutant and wild type." (PMID 19440381, 2009). "BRCA1 and BRCA2 can cause breast cancer in females, but only BRCA2 mutation confers a significant risk to men." (PMID 19584580, 2009). "Part of this familial clustering shows autosomal dominant inheritance with high penetrance due to mutations in the BRCA1 (MIM 113705) and BRCA2 (MIM 600185) breast cancer genes." (PMID 19619314, 2009). "Women who carry mutations in the BRCA1 and BRCA2 genes have a substantially increased risk of developing breast cancer and ovarian cancers as compared with the general population." (PMID 19843326, 2009). "We evaluated DNA samples from 180 Ashkenazi breast cancer BRCA1/2 positive, and from 272 patients who tested negative for these three Ashkenazi mutations." (PMID 19226467, 2009). "Cox proportional hazards regression was used to model time from birth to diagnosis of breast cancer for BRCA1 and BRCA2 carriers separately." (PMID 19843326, 2009). "Because of their strong resemblance to human BRCA1-related breast cancer, especially the mouse models of Liu and McCarthy should prove useful in preclinical therapeutic intervention studies." (PMID 19904273, 2009). "Women who carry mutations in BRCA1 and BRCA2 have a substantially increased risk of developing breast cancer as compared with the general population." (PMID 19843326, 2009). "Tumor suppressor genes, such as PTEN in Cowden syndrome and BRCA1/2 in breast cancer, function by eliciting apoptosis and G1 cycle arrest." (PMID 19830129, 2009). "In the same work it was demonstrated that BRCA1-defective HCC1937 breast cancer cells were resistant to paclitaxel as compared to MCF-7 and HCC1937WT cells." (PMID 19825178, 2009). "The Breast Cancer Information Core Database (BIC) lists more than 1560 and 1880 mutations and polymorphisms in the BRCA1 and BRCA2 genes respectively." (PMID 19329713, 2009). "Of course, current mouse models are not perfect yet and can still be further improved to closely mimic additional aspects of human BRCA1-related breast cancer, to study, for example, the role of genetic reversion in therapy resistance." (PMID 19904273, 2009). "Tumors from BRCA1-mutation carriers belong to this group of aggressive breast cancer, and accordingly EZH2 mRNA levels are also high in human BRCA1-deficient tumors." (PMID 19709408, 2009). "Patients who inherit genetic defects in BRCA1 and BRCA2 have an increased lifetime risk of developing breast cancer." (PMID 19768112, 2009). "Genetic testing for mutations in BRCA1 and BRCA2 is available in Canada for women with a significant family history of breast cancer." (PMID 19088722, 2009).
breast cancer (continued). "Our results suggest that variation in genes in IGF signaling also modify breast cancer penetrance in BRCA1 and BRCA2 carriers." (PMID 19843326, 2009). "We provide evidence that in breast cancer cells BRCA1 is involved in XIST regulation on the active X chromosome, but not in its localization as previously suggested, and that XIST can be unusually expressed by an active X and can decorate it." (PMID 19440381, 2009). "The age-standardized incidence rate of breast cancer diagnosis was estimated to be 26.94 per 1,000 per year in BRCA1 carriers (95% confidence interval (CI) = 19.79, 34.10) compared with 25.03 per 1,000 per year in BRCA2 carriers (95% CI = 18.71, 31.36)." (PMID 19843326, 2009). "Taken together, these results show that loss of BRCA1 or reduced BRCA1 expression significantly modulated TGF-β induced activation of Smad3 and Smad4 in breast cancer cells." (PMID 19768112, 2009). "The Authors reported genome-wide deficit in heterochromatin maintenance in HCC1937 BRCA1−/− breast cancer cell line." (PMID 19440381, 2009). "Relation between breast cancer receptorial status and BRCA1 mutant genotype excluding HER2 3+ cases." (PMID 19818148, 2009). "We have previously reported on epigenetic silencing of the BRCA1 gene through promoter methylation in about 10% of an unselected set of sporadic breast cancers." (PMID 19589159, 2009). "In Ontario and British Columbia, women with a strong family history of breast cancer are eligible for genetic testing for BRCA1 and BRCA2." (PMID 19088722, 2009). "Molecular screening for BRCA1 and BRCA2 mutations is now an established component of risk evaluation and management of familial breast cancer." (PMID 19298662, 2009). "In this study, we have shown frequent expression of HIF-1α in the neoplastic cells of BRCA1-related breast cancer and basal-like cancers (72 and 75%, respectively) of tumours being positive." (PMID 19724277, 2009). "We have genotyped rs744154 in 9408 BRCA1 and 5632 BRCA2 mutation carriers from the Consortium of Investigators of Modifiers of BRCA1/2 (CIMBA) and assessed its association with breast cancer risk using a retrospective weighted cohort approach." (PMID 19920816, 2009). "Accordingly, HCC1937 BRCA1−/− breast cancer cell line shows a broader compromise of the heterochromatic compartment." (PMID 19440381, 2009). "Germline mutations in the BRCA1 and BRCA2 genes account for a considerable fraction of familial predisposition to breast cancer." (PMID 19589159, 2009). "We have found that Amp13q34 is present in around 4.5% of breast cancer samples, although the rate differs slightly among tumor classes, being higher in BRCA1- (8.1%) than in BRCA2- or non-BRCA1/2- (< 3.0%) associated cancers." (PMID 19995430, 2009). "The gene expression microarray data that we use show a higher expression level of PPP1CB in BRCA1-mutant cancers than in sporadic breast cancers." (PMID 19695104, 2009). "Familial breast cancers, including those associated with heterozygous germline mutations in the major susceptibility genes BRCA1 and BRCA2, account for 5–10% of breast cancer cases in the western world." (PMID 19904273, 2009). "Wnt1-induced mouse mammary tumors share a transcriptional signature with Brca1+/− and carcinogen-induced tumors, and these in turn share components of their basaloid signature with human basaloid tumors." (PMID 19672307, 2009).